FLI1 (Fli-1 proto-oncogene, ETS transcription factor)
Diseases named in the same sentence as FLI1 in open-access papers (continued):
Sharing a sentence is not in itself a finding about the gene and the disease.
cancer (179 papers, 2003 to 2025). A tumor composed of atypical neoplastic, often pleomorphic cells that invade other tissues. "The patient's genetic findings, including the presence of an atypical EWSR1::FLI1 fusion and a possible cancer predisposition due to a CHEK2 variant, further complicate the clinical picture, necessitating a more nuanced treatment approach." (PMID 40630716, 2025). "Human FLI1 oncogene was later implicated in various types of cancers through translocations or overexpression." (PMID 38461240, 2024). "When animals from all three groups were given a 3E9 monoclonal antibody against MBG it was associated with an increase in Fli1 and a dramatic reduction of fibrosis, suggesting that CS are potentially anti-cancer substances." (PMID 33669287, 2021). "FLI1 has been shown to regulate genes and pathways associated with cancer initiation and progression, and its abnormal expression or translocation induces various types of human cancers." (PMID 34102031, 2021). "To explore the role of the EWSR1::FLI1-dependent increase in Tau expression for cancer-associated cellular phenotypes, we engineered the EwS cell line TC-32 with inducible inhibition of Tau expression and the EwS cell line TC-71 with constitutive inhibition of Tau expression." (PMID 40319030, 2025). "Moreover, a positive correlation between FLI1/UBASH3B was observed in several cancer types associated with worse prognosis." (PMID 38461240, 2024). "The network showed that the anti-cancer effect of C10 may be attributed to Fli-1 target genes and metastasis-associated genes in two sets: proliferation and apoptosis and migration and invasion." (PMID 32210104, 2020). "Increased expression of FLI1 is associated with poor survival in cancer patients." (PMID 30537986, 2018). "Notably, decreased UB-mediated degradation of ETS family transcription factors (e.g., FLI1) has been linked to cancer." (PMID 27540857, 2016). "EwS is an aggressive cancer caused by a fusion of members of the FET and ETS gene families, primarily EWSR1::FLI1." (PMID 40319030, 2025). "The biology of FLI-1 in cancer remains poorly understood, and only a limited number of studies have investigated its role." (PMID 38280044, 2024). "To examine a broader role of these UBASH genes in cancer, we examined the correlation between FLI1 and UBASH3A or UBASH3B in the TCGA database by GEPIA2." (PMID 38461240, 2024). "Among the common most affected pathways between iP300w treatment and EWS::FLI1 knockdown were “Transcriptional misregulation in cancer” and “Cellular senescence”." (PMID 39367409, 2024). "The microRNA, MiR145, controls FLI1 protein expression in cancer cells, and is a downstream target of FLI1, which negatively regulates its expression in an autoregulatory loop." (PMID 39769192, 2024). "Clusters of differentiation 99 (CD99) and the Friend leukemia integration 1 transcription factor (FLI-1) are currently accepted for the initial IHC diagnosis of ES, but they can also be expressed in other cancers." (PMID 36979853, 2023). "An increasing amount of studies have now reported that PARP-1 inhibition causes an important increase in DSB DNA damage in cancer cells expressing ETS transcription factors such as Erg, Fli1, or Ets-1." (PMID 37686260, 2023). "The SCNA comprised focal losses in 8p11.22 including the metallopeptidase genes ADAM18 and ADAM32 in 22% of lFL (q = 1.4E-15) and focal gains affecting 11q24.3 harboring cancer-associated genes ETS1 and FLI1 in 22% of lFL (q = 2E-27)." (PMID 37563306, 2023). "Fluorescent labeled MDA-MB-231 cells have been microinjected into Tg (fli1:EGFP) zebrafish embryos and used to show that Smad6 and Bmp6 expression regulates cancer cell invasion and is linked to E-cadherin expression." (PMID 37048068, 2023). "Further analysis of these differential sites revealed the increased enrichment of motifs for other ETS TFs such as FLI1, ELK4 and ELK1, which have been implicated in cancer progression, following TWEAK-induced p52 activation." (PMID 37087499, 2023).
cancer (continued). "Hypoxia inducible factor 1 subunit alpha (HIF-1-a) is the principal molecular mediator of the hypoxic response in cancer whereas EWSR1::FLI1 constitutes the oncogenic driver of EwS." (PMID 36915100, 2023). "Bioinformatics analyses and function annotation predicted that circ-FLI1 was abundant in miRNA-binding sites, and its function was mainly cancer-related." (PMID 35647294, 2022). "The peaks distribution was in agreement with publicly available FLI1 ChIP-Seq data derived from several cancer cell types." (PMID 34763718, 2021). "When analyzing experiments and clinical data it is obvious that MBG and other Na/K-ATPase inhibitors hold promise to treat cancer and following anti-CS antibody treatment to PE patients we must expect a rise of Fli1 and be alert." (PMID 33669287, 2021). "In recent years, the new antibody (e.g. ERG and Fli1) mainly expressed in the vascular endothelium can be used to mark benign and malignant tumors of vascular origin with high specificity." (PMID 33509230, 2021). "Meis1 and Fut8 gene, which are activated by Fli-1 and the LDB1 complex bound at their enhancer regions, encode two proteins, which have functions in different cancer." (PMID 33733070, 2021). "Targeted deep-sequencing analysis of the tumors at sacrifice revealed that EF-targeted xenografted tumors analyzed 6 weeks after AdV injection were composed of non-edited (85%) or partially-edited (one locus; 12% of EWSR1 or 3% of FLI1) cancer cells." (PMID 33033246, 2020). "Among immunomodulators under investigation for cancer therapy, most of the immunomodulators demonstrated that the high expression levels in the high expression FLI1 subtype via a comparison against the low expression FLI1 subtype in BRCA." (PMID 32249526, 2020). "Fli-1 is overexpressed in various cancers and diseases rendering it an important target for drug development." (PMID 30741932, 2019). "MiR-145 targets Fli-1 as well as other genes that play critical roles in progression of various cancers including those of the prostate, breast and colon." (PMID 30741932, 2019). "Among the annotated AD versus NAT top50 hypermethylated DMRs, several markers were found to be hypermethylated in various cancers including FLI1, GATA4 and NGFR." (PMID 29945573, 2018). "Remarkably, agents that increased Fli-1 transcriptional activity conferred a strong anti-cancer activity upon Fli-1-expressing leukemic cells in culture." (PMID 28052010, 2017). "Based on these abilities, much effort has been invested in the development of anti-Fli-1 drugs for the treatment of cancers driven by this TF." (PMID 28052010, 2017). "Fli-1 activation affects several hallmarks of cancer including proliferation, apoptosis, differentiation, angiogenesis, genomic instability and immune function." (PMID 28052010, 2017). "Over-expression of Fli-1 affects several hallmarks of cancer including proliferation, differentiation, apoptosis, angiogenesis and genomic stability." (PMID 28052010, 2017). "The ETS-related transcription factor Fli-1 affects many developmental programs including erythroid and megakaryocytic differentiation, and is frequently de-regulated in cancer." (PMID 28052010, 2017). "To investigate how cancer cells were eliminated in the circulation, we used 3-6 day-old larvae of a transgenic zebrafish line, Tg (fli1:EGFP), which expresses EGFP in its vascular system." (PMID 27384484, 2016). "Suppression of FLI-1 inhibits cell proliferation and induces cell apoptosis of human cancer cell by targeting Rb, GATA-1, and BCL-2." (PMID 27304058, 2016). "In this study, we demonstrate that FLI1 is overexpressed in cancer tissues as compared with the adjacent tissues." (PMID 26156017, 2015). "In future work, we will xenotransplant cancer cells into Tg(fli1:EGFP) zebrafish to observe angiogenesis occurring near the cancer cells in live animals." (PMID 25171174, 2014).
cancer (continued). "The status of Fli-1 in different cancers and the clinical implications of their expression during cancer development still need further investigation." (PMID 24923303, 2014). "Most attention about Fli-1 in cancer has been paid to Ewing’s sarcoma and hematologic malignancies." (PMID 40305194, 2025). "Indeed, Fli-1 transcriptional activation affects several hallmarks of cancer, including proliferation, survival, differentiation, angiogenesis, genomic instability, and immune surveillance." (PMID 38461240, 2024). "FLI1 is a powerful oncogene that promotes the progression of diverse cancers." (PMID 39769192, 2024). "In addition to cancer, FLI1 plays critical roles in hematopoietic stem cell maintenance and development of various mature blood cells." (PMID 39769192, 2024). "Abnormal expression of Fli1 induced different kinds of human cancers and auto-immune diseases." (PMID 39451223, 2024). "Genes normally repressed by EWS::FLI1 but upregulated in EWS::FLI1 "low states", including LOX, TGF-beta, FN1, SPARC, and NT5E, have been implicated in MDSC recruitment or activity in other cancers." (PMID 36505823, 2022). "Next, cancer cells were injected into the midbrain of 2 dpf Tg (fli-1: EGFP) zebrafish to evaluate whether the cancer cells could proliferate at 4 dpi." (PMID 34801071, 2021). "Furthermore, FLI1 is related to transcriptional misregulation in cancer and NF-κB signaling pathway." (PMID 34370778, 2021). "To explore the pan-cancer expression pattern of FLI1, we used TISCH at the single-cell level." (PMID 33971970, 2021). "Fli1 was first identified in cancer, systemic sclerosis and tissue fibrosis." (PMID 33669287, 2021). "To explore the molecular mechanism of C10 in cancer cell proliferation and apoptosis in an Fli-1-dependent manner, we evaluated the expression of Fli-1 target genes along with apoptosis and metastasis-associated genes in PC3 cells after treatment with different concentrations of C10." (PMID 32210104, 2020). "However, the roles of FLI1 expression level in many types of cancers were only studied by a few researchers, and the results were often conflicted." (PMID 32249526, 2020). "Thus, this work identifies novel inhibitory compounds that can be used for the treatment of cancers driven by overexpression of Fli-1." (PMID 30741932, 2019). "Here, we additionally show that ERG and FLI1 expression is also downregulated in cancer pathology." (PMID 30500808, 2018). "Our work delineates the role of ERG and FLI1 in ECs, and suggests that maintaining the expression of these TFs may be possible therapeutic options for various EndMT-related diseases including cancer." (PMID 30500808, 2018). "The observation of strong Fli-1 expression in adenoid-like differentiated NPC suggests that NPC cancer cells might develop adenoid-like endothelium consequent to Fli-1-mediated gene expression." (PMID 28418872, 2017). "Further speculation suggests that Fli-1 is widely expressed in various cancer tissues but plays different, tissue-specific roles." (PMID 28418872, 2017). "Based on these diverse biological properties, Fli-1 may be an excellent therapeutic target for various diseases and cancers that are driven by high levels of this ETS factor." (PMID 28052010, 2017). "However, FLI-1 overexpression, probably as a result of promoter hypomethylation, has been detected in various types of cancer and other diseases." (PMID 25986394, 2015). "Additionally, FLI1 (which had been identified in our selected differentially methylated probe sets for 8 of 14 cancer types), contained a combination of CIMP + Hyper and CIMP + Hypo regions, which occurred at the gene promoter and the first exon, respectively." (PMID 25960768, 2015). "It was speculated that Fli-1 were widely expressed in various cancer tissues while it specifically played different roles." (PMID 24923303, 2014). "ERG, ETV1, ETV4, ETV6, FLI1, and FEV, are implicated in the pathogenesis of several cancers." (PMID 21789226, 2011).
cancer (continued). "Thus, the beneficial effect of inhibiting Fli-1 in cancer cells may, at least in part, be attributed to decreased inflammation." (PMID 40305194, 2025). "Interestingly, the silencing of FLI-1 not only suppressed cancer stem cell properties in vitro but also hindered tumorigenesis in vivo, suggesting that FLI-1 could be a promising target for future therapeutic approaches in TNBC." (PMID 38473804, 2024). "Several of these genes are known oncogenes and tumor suppressors including Nf1, Pten, Myc and Fli1, while many others have not been directly associated with cancer and could be potential targets for therapy." (PMID 24827933, 2014). "FLI1, a transcription factor in the ETS family, plays crucial roles in hematopoietic system development, angiogenesis, and cancer." (PMID 40536817, 2025). "Friend leukemia virus integration 1 (FLI1), an ETS transcription factor, regulates a broad spectrum of biological processes, including cancer development, fibrosis, and inflammation." (PMID 39140108, 2024). "The role of FLI1 in cancer has been increasingly reported, and FLI1 is a predictor of poor prognosis in patients with BRCA and promotes the metastasis and cancer stem cell properties of BRCA cells." (PMID 38448802, 2024). "Both AURKA and AURKB are known to be upregulated in many cancers and their expression has been shown to be regulated by the EWSR1/FLI1 fusion." (PMID 39518006, 2024). "The dysregulation of E2F family transcription factors is also known to promote cancer and it has been reported that in EWS, the transcription of EWSR1/FLI1 target genes is partially mediated by E2Fs." (PMID 39518006, 2024). "Cancer chemotherapeutics including camptothecin (CPT), the CPT analog topotecan (TPT), and etoposide (ETO) were shown to be potent Fli-1 protein inhibitors)." (PMID 36074578, 2022). "Using cancer cell line RNA-seq data, we first identified 516 genes that were commonly downregulated (>1 FPKM expression and ≥2-fold down) by EWSR1::FLI1 knockdown in three well-characterized EwS cell lines, SK-N-MC, A673, and CHLA-10." (PMID 35705030, 2022). "In support of these observations, a CCLE (Cancer Cell Line Encyclopedia) analysis predicted high expression of WAS and WIP in FLI1-positive hematological malignancies." (PMID 33717090, 2021). "Understanding of the role of Fli1 and MBG in the development of PE gives us a possibility to suggest CS as one of the therapeutic tools for the treatment of cancer." (PMID 33669287, 2021). "The transgenic strain Tg(fli1:EGFP) has green fluorescent blood vessels and represents a suitable model for the study of cancer migration processes." (PMID 33772505, 2021). "While many studies have demonstrated that Fli1 is a pro-cancer factor, CS including MBG are becoming attractive anti-cancer drug candidates." (PMID 33669287, 2021). "The Tg(fli1:GFP) transgenic line used in this study allowed us to visualize blood vessels in the living host and to allow for the analysis of cancers cells after their intravasation into the blood vessels." (PMID 32610610, 2020). "Among the cancer driver genes that experienced epigenetic changes in at least five cancer types, we identified eight genes: CEP55, PIF1, RRM2, NCAPH, ZEB2, CIT, FLI1, and PCDH17." (PMID 31900418, 2020). "Inhibitors abrogating FLI1, MEF2C, ELK3, or SP4 activation have been previously shown to have efficacy in different cancers." (PMID 33218352, 2020). "To these sets, we added 59 definitions of modules from Atlas of Cancer Signaling Network (ACSN) and the set of potential transcriptional targets of EWS/FLI-1 chimeric oncogene." (PMID 26925094, 2016).
cancer (continued). "These include a number of known or potential tumour suppressor genes (BCSC-1, CHEK1, ST14, ATM, P53AIP1), genes with proposed roles in cancer progression (BARX2), apoptosis (PIG8, P53AIP1) and oncogenesis (FLI1, ETS1), and a DNA damage-inducible gene (DDI1)." (PMID 18506147, 2008). "FLI1 is a member of the ETS transcription family, and subsequent studies have shown broader activity of YK-4-279 against other ETS transcription factors in other cancers." (PMID 39448867, 2025). "The roles of SRGN, FLI1, and MACROH2A2 in carcinogenesis within other cancers are established, yet their mechanisms of action in uEVs of BC remain unclear." (PMID 39816677, 2025). "Since Fli-1 is a key regulator of various cytokines and chemokines, including IL-6, CCL2, CCL5, CXCL2, and CXCL13, the role of Fli-1 in promoting cancer development may partly be due to its role in driving the expression of these inflammatory mediators." (PMID 40305194, 2025). "Multiple investigations show the oncogenic roles of SRGN, FLI1, and MACROH2A2 in various cancers." (PMID 39816677, 2025). "In summary, our findings identify LOXHD1, which is transcriptionally silent in the vast majority of normal and cancer cells, as a direct EWSR1::FLI1 target gene that plays an important role in cytoskeletal homeostasis, hypoxic adaptation, and oncogenic transcription in EwS." (PMID 35705030, 2022). "Therefore, theoretically, in cancer patients and experimental animals, MBG should suppress the levels of Fli1, an oncogene." (PMID 33669287, 2021). "We demonstrated that A661 and A665 inhibit proliferation not only of cancer cells expressing Fli-1, but also of cancer cells lacking Fli-1 expression." (PMID 30741932, 2019). "ERG and FLI1 genes are closely related members of the erythroblast transformation-specific (ETS) family of transcription factors, and studies have proved that these two TFs were usually involved in various types of cancer jointly." (PMID 26425543, 2015). "In cancer, the abnormal expression of oncogenic transcription factors (e.g., FLI-1 and ERG) as well as negative regulators of carcinogenesis (e.g., FEV) in the ETS family induces the upregulation of genes that are known to promote cancer and the downregulation of genes that subdue cancer." (PMID 35548776, 2022). "Two significantly enriched pathways in LUAD and their related DEmRNAs, namely transcriptional misregulation in cancer (TGFBR2, FLI1, ERG and SIX1) and central carbon metabolism (NTRK3 and SLC7A5), were speculated to play key roles in LUAD regulated by DEmiRNAs." (PMID 30761256, 2019).